INS (insulin)
Diseases named in the same sentence as INS in open-access papers (continued):
Sharing a sentence is not in itself a finding about the gene and the disease.
Hypoglycemia (continued). "While we consider this anecdotal evidence of the insulin-sensitizing effect of CL (none of the vehicle-treated animals experienced hypoglycemia), future studies should perform the gold standard glucose clamp procedure in order to more accurately assess insulin sensitivity." (PMID 30804793, 2019). "The closed-loop algorithm continually adapts to changing insulin needs during the day and between days, allowing increases in time spent in the target glucose range and lowering of mean glucose concentration without increasing time spent in hypoglycaemia." (PMID 30935872, 2019). "We showed that an increased proportion of time was spent in the target glucose range and mean glucose was reduced with fully closed-loop insulin delivery compared with standard insulin therapy, without an increase in the time spent in hypoglycaemia or the total daily insulin dose." (PMID 30935872, 2019). "Indeed, CX3CR1−/− mice with impaired neuron-to-microglia communication did not display overt microglia activation and did not develop hypoglycemia in response to insulin challenge." (PMID 30996341, 2019). "A basal reduction; for those on insulin pumps a basal rate reduction of 20% for 6 h, or for those on MDI a 20% basal dose reduction in combination with a carbohydrate snack at bedtime, can reduce the incidence of nocturnal hypoglycemia in response to a prior bout of afternoon exercise." (PMID 31258513, 2019). "Although glycogenolysis, gluconeogenesis, and negative feedback of insulin secretion are protective against fasting-induced hypoglycemia in normal physiology, they may not have the same impact in individuals with T1DM." (PMID 31866948, 2019). "Similarly, for HypoSevere the fully adjusted odds of hypoglycemia were greater for basal insulin non-users but not for basal insulin users." (PMID 31775749, 2019). "The CL-induced hypoglycemia during the ITT may have been attributed to the effect of CL to increase insulin secretion, but since insulin levels were not measured throughout the ITT, this is an important assessment that should be done in future studies." (PMID 30804793, 2019). "In addition, both patients who are not achieving their A1C targets, and their physicians, cite hypoglycaemia as a barrier to effective insulin titration." (PMID 31294087, 2019). "Insulin levels are not useful unless the hypoglycemia is non-ketotic or hypoketotic." (PMID 31700521, 2019). "However, the time spent in hypoglycemia during the 2-days of CHO-loading was 10.4% and therefore a lower insulin dose might be suggested to reduce the time spent in hypoglycemia." (PMID 31496994, 2019). "This could be a compensatory mechanism to protect against hypoglycemia in response to exaggerated insulin release when little or no glucose is absorbed into the blood." (PMID 31777424, 2019). "Additionally, the measurement of insulin antibodies is recommended, however, not necessarily during the hypoglycemia." (PMID 31777577, 2019). "Strategies for exercise performance may focus on matching carbohydrate intake to the specific nutritional requirement of the activity (rather than hypoglycemia prevention) and insulin doses should be increased accordingly." (PMID 31258513, 2019). "Our multicentric, observational, cross-sectional study aimed to evaluate the basal/total ratio of daily insulin dose (b/T) in a large series of DM1 and DM2 patients by looking for a possible relationship with the glycemic control (as evaluated by HbA1c) and the occurrence of hypoglycemia." (PMID 30918874, 2018). "According to one recent cost-effectiveness analysis, the addition of NPH insulin to metformin and sulfonylurea combination therapy is the most cost-effective strategy; however, the use of a DPP-4 inhibitor is potentially cost-effective when higher rates of hypoglycemia are assumed." (PMID 29713649, 2018).
Hypoglycemia (continued). "Of these, 9/27 (33.3%) had presented on another occasion with a fall, compared to 4/52 (7.7%) insulin-treated patients without a documented episode of hypoglycaemia, p = 0.008; and a higher proportion had presented with unsteadiness (5/27, 18.5% vs 2/52, 3.9%), p = 0.043." (PMID 28918198, 2018). "In addition, a biochemical analysis indicated hypoglycemia, without increased serum insulin and C-peptide, but with increased glucagon levels, as the possible influence of glibenclamide overdose." (PMID 30595699, 2018). "A closed-loop system with accurate continuous glucose monitoring and computer-assisted titration of insulin based on glucose measurements could permit tight GC without increasing hypoglycemia and nursing staff workload." (PMID 30071851, 2018). "Furthermore, titration should be revisited when the patient is not achieving goal, hypoglycemia occurs, or there is a change in the insulin type or brand (e.g., biosimilar)." (PMID 29476414, 2018). "In the case of effects of insulin-induced hypoglycemia on ECG, this study showed that there was the development of arrhythmia in two patients and the increase in heart rate, QRSd, and QTc interval at hypoglycemia compared with the other time points during CPST." (PMID 30105256, 2018). "A potential confounder of our interpretation of the effects of hyperinsulinemia was the administration of sugar-sweetened drinking water to insulin-infused mice; however, in the absence of this dietary change, mice develop relative hypoglycemia, which would have its own set of confounds." (PMID 30249002, 2018). "Semi-annual surveys confirmed that during year 03 to year 08 after BCG vaccinations there were no reports of severe hypoglycemia by any patient, even with lowered HbA1Cs near the normal range, and no change in their care as it related to new insulin pumps or continuous glucose monitoring devices." (PMID 29951281, 2018). "However, the routine clinical use of topical insulin for wound management is not generally accepted as a first-line treatment, and significant adverse effects—including life-threatening hypoglycemia—have been reported." (PMID 29447281, 2018). "On the other hand, the downregulation in insulin signaling in the liver may not be sufficient enough in preventing hypoglycemia." (PMID 29760586, 2018). "The number of days without insulin or with non-adherence is higher among patients with obstacles to insulin use (they had more difficulty in applying the injection and were not satisfied with the flexibility of insulin injections or presence of hypoglycemia)." (PMID 29791677, 2018). "In this study, we show that insulin is not driving the hypoglycemia, since insulin levels were not increased in infected Adx mice and potent inhibition of insulin release by clonidine could not reverse the hypoglycemia." (PMID 30375380, 2018). "For those individuals taking long-acting insulin with or without short-acting insulin, a 5.4% rate of recurrent hypoglycemia leading to return ED visits would also be considered a frequency in which disposition decisions should be considered on a case-by-case basis." (PMID 29799604, 2018). "The initiation of insulin therapy did not affect the relationship between hypoglycaemia and QoL." (PMID 28803366, 2018). "We hypothesize that those who experience hypoglycaemia will have a less increase in QoL after transition to insulin compared to those who do not experience hypoglycaemia." (PMID 28803366, 2018). "In insulin-treated patients with documented hypoglycaemia, 20/27(74%) attended on another occasion with a “hypo clue” symptom, compared to 21/52(40%) of those without hypoglycaemia, p = 0.008." (PMID 28918198, 2018). "In this study, we used insulin pump 712E (Medtronic Incorporated, Northridge, USA) delivered insulin in both groups, our data showed that patients treated with the metformin add-on CSII therapy had significantly decreased incidences of hypoglycemia (blood glucose <3.9 mmol/L)." (PMID 29946148, 2018).
Hypoglycemia (continued). "Also, one episode of hypoglycemia occurred following a motor vehicle accident and medical records indicated the patient was not taking insulin as prescribed; no other episodes of symptomatic hypoglycemia requiring assistance were reported." (PMID 29417495, 2018). "However, MDI and CSII are not nearly as efficient as the endogenous insulin secretion; as a result, acute events do occur, exposing patients to severe hypoglycemia or diabetic ketoacidosis." (PMID 32232090, 2018). "Importantly, by contrast to direct topical administration insulin, which can cause life-threatening hypoglycemia, pharmacological inhibition of IDE possesses no intrinsic risk of triggering hypoglycemia." (PMID 29447281, 2018). "The finding that unsteadiness was the other most notable discriminatory symptom may be consistent with this: 15% vs 4% (or 19% vs 4% of insulin-treated) patients with/without hypoglycaemia on another occasion presented with unsteadiness." (PMID 28918198, 2018). "The strengths of our experimental approach are that we studied defined molecular perturbations in GCK and used insulin clamp techniques across all models to create carefully controlled and matched hypoglycemic challenges (as opposed to insulin bolus-induced hypoglycemia or glucoprivation)." (PMID 30146176, 2018). "In contrast, a prospective observational cohort study in 2007 (n = 157) found no statistical difference in the incidence of hypoglycaemia, rate of glucose reduction, or length of hospital stay and concluded that an initial bolus of intravenous insulin offered no significant clinical benefit or harm." (PMID 28659865, 2017). "Obviously, it is essential to T2D patients to achieve and maintain the glycemic control, preferentially without adding basal insulin therapy, because it was related to increased number of patients experiencing hypoglycemia during 1 year of follow-up of basal insulin therapy." (PMID 28812028, 2017). "The patients receiving insulin glargine were administered more insulin injections and total units of insulin without increased episodes of hypoglycemia, which may have impacted the blood sugar readings." (PMID 28970434, 2017). "Late in pregnancy, with the rise in insulin resistance, clinical hypoglycemia can be absent or attenuated, so the tumors may be masked." (PMID 28427440, 2017). "However, both conditions in which glucose was low but insulin was either high (injection) or low (fasting) were protective, suggesting that it is the hypoglycemia and not the effects on insulin level that mediate the resistance to chemotherapy treatment." (PMID 28358805, 2017). "The present study demonstrates that SGLT-2 inhibitors are effective as adjunct therapy to insulin in T1DM, heralding improved glycemic control, reduced body weight and total daily insulin dose without an increase in total AEs, hypoglycemia, or genital and urinary infections." (PMID 28276512, 2017). "Considering the fact that lens is an insulin‐independent tissue and not capable to downregulate the glucose transport, the strict application of insulin unavoidably increases the incidence of severe hypoglycemia fourfold to sixfold." (PMID 28722304, 2017). "There were nonsignificant hypoglycemia events between basal insulin groups and the results for the last or seventh day of treatment may not be clinically significant in practice." (PMID 28970434, 2017). "However, in the current study, animals were injected with STZ three days prior to the experiment and were never exposed to hypoglycemia or exogenous insulin until the study day." (PMID 28570686, 2017). "Although the biochemical profile mimicked that of hyperinsulinism, no detectable insulin nor insulin-like substances were detectable at the time of hypoglycemia, and glucose infusion rates required to maintain euglycemia were much lower than are required in bona fide hyperinsulism." (PMID 28541532, 2017).
Hypoglycemia (continued). "Whole-body BMAL1 knockout mice presented with diminished gluconeogenesis and could not recover from insulin-induced hypoglycemia." (PMID 28352282, 2017). "Additionally, as expected from the exposure to insulin treatment, the insulin-treated LADA patients had an increased frequency of hypoglycemia compared with the non-insulin treated T2DM patients." (PMID 29062603, 2017). "Insulin is the main treatment for T1DM patients, and human islet transplantation also has emerged as a treatment, since insulin may cause severe hypoglycemia and some patients are not sensitive to insulin." (PMID 29127315, 2017). "However, if the administrated amount of insulin is correct, no hypoglycemia should occur during exercise, resulting in a normal physical fitness." (PMID 29259658, 2017). "Second, we were unable to capture medication or other treatment changes that can affect BG excursions, which could be relevant to the increased likelihood of hypoglycemia seen in members who reported not using insulin at the beginning of the program." (PMID 28698167, 2017). "Both of this, i.e. high glucose and insulin infusion rather than bolus, will result in a high glucose/insulin ratio at any given time, which may protect from hypoglycemia." (PMID 28245289, 2017). "Furthermore while PACAP has been shown to contribute to the glucagon response to insulin-induced hypoglycaemia in mice administration of Ex-4 did not produce hypoglycemic effects in T2D patients." (PMID 27305000, 2016). "However, given that the changes in HbA1c from baseline to Week 24 in the study by Schoberet al. were different to those in the present study, and that insulin dose was not presented, this comparison of hypoglycaemia between both studies is limited." (PMID 27887605, 2016). "The incidence of hypoglycemia, which is an important component of safety, increased significantly with addition of sulfonylureas, glinides, or insulin, but did not increase significantly with alfa-glucosidase, DPP4 or SGLT2 inhibitors, GLP1 agonists, or thiazolidinediones 39-41." (PMID 27546934, 2016). "In this regard, repeated hypoglycemia leads to a defect in hypoglycemia-induced activation of counter-regulatory mechanisms (namely, an attenuation of the normal epinephrine response to hypoglycemia, whilst insulin is not reduced and glucagon not increased by low glucose)." (PMID 26918849, 2016). "However, during the phase of recovery from hypoglycemia, plasma glucose levels remained significantly lower in GCLM-KO mice compared to WT at times 60 min (−27.9%; p = 0.001), 90 min (−44.6%; p = 0.001), and 120 min (−41.2%; p = 0.004) post-insulin-injection." (PMID 27148080, 2016). "The questionnaire did not record insulin regimen or sulphonylurea use, both of which could contribute to regional differences in the rate of hypoglycaemia." (PMID 27161418, 2016). "For the doses examined, SQ regular insulin lowered MGC and GV without causing hypoglycemia." (PMID 26819233, 2016). "However, these two studies have not reported the levels of hypoglycaemia achieved with these insulin concentrations." (PMID 27843452, 2016). "The results of the present study demonstrate that insulin-induced hypoglycemia may result in acute neuropathic pain and the increased mechanical sensitivity noted is the result of decreased glycemic levels rather than insulin itself." (PMID 26824041, 2016). "In a cohort of approximately 5000 adult T1DM patients, higher variability in individual basal rates correlated to an increased prevalence of severe hypoglycemia and diabetic ketoacidosis, independent of total daily insulin, age, duration of disease, and gender." (PMID 26938444, 2016). "Overall, CHI resolved in 15 (71%) children in this cohort at age 3.1 (0.2, 13.0) years with age appropriate fasts in hospital (16–20 h) demonstrating absence of hypoglycaemia, suppressed insulin secretion and robust ketotic responses supported by satisfactory home glucose monitoring." (PMID 27908292, 2016).
Hypoglycemia (continued). "In addition, our results also suggest that in regard to HbA1c-lowering efficacy, a low-dose of glimepiride is similarly effective as sitagliptin without weight gain or severe hypoglycemia at the early stage of T2DM with low insulin secretion." (PMID 26925169, 2016). "The difference of goal achievements might be attributed to the fact that insulin titration was not optimal due to fear of hypoglycemia particularly in patients on a low carbohydrate diet." (PMID 26986104, 2016). "The incidence of hypoglycemia was not markedly different among the types of insulin regimens." (PMID 27316668, 2016). "For instance, other possibilities are that KD induces effects by promoting hypoglycaemia, lack of fluctuations of insulin blood levels, or by lowering the activity of the so-called nutrient-integrating pathways that sense and respond to fluctuations in nutrient levels." (PMID 27245682, 2016). "Notably, these very low glucose concentrations are not reached under in vivo conditions, even after insulin-induced hypoglycaemia." (PMID 26108563, 2015). "Interestingly, different from insulin alone, Cmpd1 combined with insulin showed enhanced efficacy and duration of action without increased hypoglycemia." (PMID 25799496, 2015). "It therefore appears that hypoglycemia, and not insulin per se, has anapyrexic potential." (PMID 30873441, 2015). "Similarly, 54.0% patients using insulin therapy, 44.0% using SU agents, and 37.4% not using insulin or SU agents had knowledge of symptoms but experienced by hypoglycemia." (PMID 26566411, 2015). "Finally, merely 29.4% patients receiving insulin therapy, 19.7% using SU agents, and 14.7% not using insulin or SU agents had low recognition about times when hypoglycemia was likely to occur." (PMID 26566411, 2015). "When insulin treatment was excluded, which is not shown in the figure, the frequencies of hypoglycemia for the last 1 month and the last 1 year were 3.8% and 8.8%, respectively, according to the physicians, and 6.1% and 13.8%, respectively, according to the patients." (PMID 26566411, 2015). "The stabilization of insulin doses during the baseline periods may have also contributed to the fact that a patient’s BMI did not significantly influence the frequency of hypoglycemia among lixisenatide treated patients." (PMID 26594250, 2015). "Additionally, lack of assistance from family members at the time of the insulin injection and current drinking were predictors for mild hypoglycemia." (PMID 26102197, 2015). "This improvement in A1C was achieved with a nonsignificant incidence of hypoglycemia or change in body weight, which could be concerns regarding the safety of a self-titration insulin regimen." (PMID 25904987, 2015). "Using a threshold of <3.9 mmol/L, the rates of patients with overall hypoglycemia, daytime hypoglycemia, and nocturnal hypoglycemia were 25.1 %, 20.5 %, and 7.6 %, respectively, during treatment with insulin glargine; and 23.2 %, 18.3 %, and 10.8 %, respectively, during treatment with NPH insulin." (PMID 26055391, 2015). "When blood glucose levels are low in patients with non-iatrogenic hypoglycemia, insulin secretion is promptly suppressed and counter-regulatory hormones, such as glucagon, catecholamines, cortisol, and growth hormone, are secreted in considerable quantities, elevating the blood glucose level." (PMID 25192953, 2015). "In addition, those who received intensive insulin therapy had a 3.0-fold (36.6% vs. 12.2%, p = 0.010) higher proportion of patients who experienced severe hypoglycemia, compared with those who did not receive intensive insulin therapy." (PMID 26102197, 2015). "The results from the SOLVETM cohort in Turkey are consistent with previously reported randomised clinical trials and non-investigational study data of insulin detemir with regard to effective glycaemic control, low incidence of hypoglycaemia and a weight-sparing effect." (PMID 25048824, 2014).